RET (ret proto-oncogene)
Diseases named in the same sentence as RET in open-access papers (continued):
Sharing a sentence is not in itself a finding about the gene and the disease.
tumor (continued). "The low intratumoural heterogeneity within the tumour cell population supports the use of targeted RET inhibition in advanced-stage patients, as exemplified by the case presented." (PMID 40729029, 2025). "In preclinical models, combination therapy has been shown to suppress both EGFR- and RET-driven signaling, resulting in enhanced tumor regression compared to monotherapy." (PMID 40416863, 2025). "Supported by favorable pharmacokinetics, BYS10 achieved robust anti-tumor efficacy in diverse RET-driven xenograft models." (PMID 41181595, 2025). "The development of RET-selective inhibitors provides an opportunity for precision therapy in those proven to have RET-driven tumours, particularly MTC, PTC and NSCLC." (PMID 40138217, 2025). "Tumor-agnostic approvals have a portfolio of TMB, dMMR, MSI, NTRK fusion, RET fusion, and BRAF mutations; each of which is actionable by giving a specific class of FDA-approved agents." (PMID 40183077, 2025). "In the limited subgroup of selpercatinib-treated patients, this correlation remained significant, suggesting better RET inhibition in the presence of a high tumor burden with high glycolytic activity." (PMID 40524205, 2025). "By blocking RET signaling pathways, the selective RET inhibitors can effectively inhibit tumor growth, reduce the spread of cancer, and improve patients' outcomes." (PMID 40237476, 2025). "Lenvatinib targets multiple pathways, including RET, to inhibit tumor growth, while pembrolizumab enhances immune response." (PMID 40363930, 2025). "Currently, tumour-only sequencing is the standard approach, using a multigene panel to analyse multiple somatic drivers, including RET." (PMID 40138217, 2025). "Sorafenib is suggested as an inhibitor of the growth of RET-driven tumours through a combination of different mechanisms, and it targets both VEGF-dependent tumour angiogenesis and RET-dependent TC proliferative cells." (PMID 40332222, 2025). "High expression of RET is associated with reduced survival in NB patients, and inhibition of RET with Vandetanib or Cabozantinib decreases tumor growth in cell lines and mouse models." (PMID 41516252, 2025). "In ACC, a key signaling axis involves tumor-derived CCL2 recruiting CCR2+ TAMs, which in turn secrete GDNF to drive tumor cell proliferation via the RET pathway." (PMID 41164198, 2025). "The approval was based on data from the LIBRETTO-001 trial, which evaluated 41 patients with RET fusion-positive tumours, excluding non-small-cell lung cancer and thyroid cancer." (PMID 40141188, 2025). "The genomic landscape of Spitz neoplasms includes fusions in genes such as ALK, ROS1, MET, RET, or BRAF and mutations in HRAS genes, which influence both the tumor’s biological behavior and morphological features." (PMID 40870546, 2025). "We detected kinase fusion in 2 cases (3.2%) of the tumours: RET fusion in 1 case, and NTRK3 fusion in another case." (PMID 40144205, 2025). "We confirmed the presence of both BRAF V600E and RET S649L in this earlier metastasis, indicating that RET S649L was an early event in tumor progression." (PMID 40756116, 2025). "Given the limited data on RET's carcinogenic effects, this study aims to evaluate its tumour‐initiating potential using SAR predictions and an in vivo Swiss albino mouse model." (PMID 40211435, 2025). "Concurrently this study enrolled a tumour-agnostic population of patients with RET fusion-positive advanced solid tumours." (PMID 41465387, 2025). "In vitro studies have shown selpercatinib’s potent efficacy in suppressing the proliferation of diverse cancer cell lines with RET alterations, while in vivo models have demonstrated its ability to induce tumour regression." (PMID 40141188, 2025). "Zeteletinib has demonstrated strong anti-tumour activity in RET-altered tumours, with a 44% response rate in MTC patients." (PMID 40332222, 2025).
tumor (continued). "Tyrosine kinase inhibitors (TKIs) are used to treat RET gene fusion-positive tumours by blocking the activity of the abnormal RET protein, inhibiting cancer cell growth." (PMID 40141188, 2025). "RET gene fusion-positive tumours result from the fusion of RET with another gene, producing an abnormal RET protein that promotes cancer growth." (PMID 40141188, 2025). "The same mutation as in the primary tumour and LNM (RET gene (chr10:43609933; c.1886_1891delTGTGCG; p.Leu629_Asp631delinsHis; coverage: 1983; allele frequency: 26.83%)) was detected in the present sample of DM." (PMID 40729029, 2025). "CaMKII promotes tumor growth in follicular cell-derived PTC by activating the ERK pathway signaling in response to RAS or RET/PTC oncogenes." (PMID 41008599, 2025). "The results identified a RET A641R mutation (variant allele frequency [VAF], 28.3%), an H3-3B R9C mutation (VAF, 39.3%), and an XPO5 R519Q mutation (VAF, 25.6%) (estimated tumor cell content, 70.0%)." (PMID 40638225, 2025). "Although the RET exon 2–11 deletion was classified as a VUS, it was the only detectable alteration in the progressive tumor, and it involved the functional kinase domain of RET, suggesting potential oncogenic activity." (PMID 40606448, 2025). "Among them, high iodine intake is a high-risk factor for BRAF gene mutations in PTC patients; RET gene testing can be performed for MTC patients, and RET mutations are closely related to tumor invasiveness and poor prognosis." (PMID 41323380, 2025). "MKIs target RET (rearranged during transfection), as well as other receptors involved in tumor angiogenesis and cell proliferation." (PMID 41465145, 2025). "The choice for a RET-specific inhibitor TKI is based on the presence of a RET alteration, determined in a tumor biopsy." (PMID 40524205, 2025). "RET inhibitors have shown effectiveness in reducing tumor development and inducing significant responses in individuals with RET-altered malignancies." (PMID 38501105, 2024). "Mutations in genes such as BRAF, RET/PTC, and RAS lead to uncontrolled cell proliferation and tumor growth." (PMID 39767725, 2024). "Based on this aspect, patients with RET PV need to be carefully followed as they can develop a second tumour, up to 20 years after the first diagnosis." (PMID 39673085, 2024). "Here, we present the safety, tolerability and preliminary anti-tumor activity of SY-5007 in patients with RET-altered solid tumors from a first-in human, multicenter, open-label, phase 1 dose-escalation and dose-expansion study." (PMID 39489747, 2024). "ALK rearrangements were more frequent in non-drinkers (5.95% vs. 1.05%, P = 0.047) and patients with advanced stages (6.81% vs. 3.26%, P = 0.025), and RET fusions were more common in patients with normal tumor markers (4.92% vs. 1.35%, P = 0.007)." (PMID 39364008, 2024). "Further analysis of DEGs in the pseudotime trajectory showed early high expression of CALM1 and CALM2 in the subcluster 1, and late up-regulation of RET in the subcluster 2, suggesting the persistent dysregulation of kinase signals over tumor evolution." (PMID 38407266, 2024). "From The Cancer Genome Atlas (TCGA) and the Gene Expression Omnibus (GEO) databases, all available ROS1+ (n = 10), ALK+ (n = 5) and RET+ (n = 5) NSCLC tumor and ROS1+ cell line (n = 7) RNA-sequencing files were collected." (PMID 39737401, 2024). "RET alteration results in the interaction changes between tumor cells and the host, which trigger the nodal metastasis of PTC." (PMID 38734621, 2024). "RET-TKIs provided significant benefits to patients, and a decline in tumor markers was observed, which is consistent with previous studies." (PMID 39628994, 2024). "Although no genes regulated through the Notch signaling pathway were significantly dysregulated, we found that NOTCH1 expression decreased significantly in ROS1+ tumor samples compared to RET+ specimens (p=0.04)." (PMID 39737401, 2024).
tumor (continued). "While the p.C634W variant also activates the RET pathway, its effect is generally less potent than that of p.M918T, resulting in a more moderate increase in RET signaling and a less aggressive tumor phenotype." (PMID 39595993, 2024). "Tumor tissue and plasma cfDNA sequencing revealed a rare somatic in-frame RET deletion [NM_020975.6(RET):c.2694_2705del] in the MTC patient reported here." (PMID 38438731, 2024). "In the future, it is expected that combined immuno- and endoradiotherapies will gain significance in personalized medicine, especially for established tumor mutations like BRCA, RET, and BRAF." (PMID 38256909, 2024). "Given its favorable safety profile and potent anti-tumor activity, SY-5007 is a promising candidate for combination therapies in RET-altered solid tumors." (PMID 39489747, 2024). "In papillary thyroid carcinoma (PTC) and non-small cell lung cancer (NSCLC), RET fusion proteins that are constitutively active and promote tumor growth have been identified in 13-43% and 2% of patients, respectively." (PMID 39931212, 2024). "The expression of RET was the highest in normal controls, and RET was downregulated in terms of stage, grade and tumor size in BC patients." (PMID 38532419, 2024). "Evidence from the LIBRETTO-001 trial underscores selpercatinib’s prowess, demonstrating promising outcomes across various tumor types with RET fusion-positive profiles." (PMID 39272672, 2024). "Knocking down or pharmacologically inhibiting the RET kinase in various mouse and human neuroendocrine PCa models significantly diminished PCa tumor growth and cellular vitality." (PMID 38957390, 2024). "The exome analysis of the initial tumor revealed mutation in two genes, RET and POLE, which were also present in all the cells of the initial and in the tumor recurrence." (PMID 39273494, 2024). "This is where selective RET inhibitors come into play, as they effectively block RET signaling, thereby halting tumor growth and potentially inducing tumor regression." (PMID 39272672, 2024). "Receptor tyrosine kinase is an enzyme-linked receptor involved in the proliferation and invasion of a variety of cells, and RET G533C mutation can accelerate the proliferation and invasion of CRC tumor cells." (PMID 38699694, 2024). "We recommend continued vigilance for neoplasms driven by dysregulated downstream MAPK signalling in patients undergoing selective RET inhibition." (PMID 38804700, 2024). "Biomarker analysis of 61 patients with circulating tumor DNA (ctDNA)-detectable RET alterations showed an ORR of 57.4% and median PFS of 13.8 months." (PMID 39489747, 2024). "As the first step to evaluate the efficacy of MitoQ and its combination with selpercatinib in RET-mutant tumor cells, we validated that mitochondrial enrichment of its functional moiety, ubiquinone, is critical for its growth inhibitory effects in TPC1 cells." (PMID 38378752, 2024). "And RET fusions are substantially more common than NTRK fusion, BRAFV600E and RAS mutations in aggressive tumor behavior, which includes high rates of lymph node and distant metastases." (PMID 39600648, 2024). "In contrast to SGT, CGP platforms typically can evaluate many tumor agnostic biomarkers, including BRAF V600E, MMR deficiency/MSI status, TMB assessment, NTRK fusions, and RET fusions." (PMID 39544293, 2024). "MEN syndrome is an umbrella term used to describe a family of tumor syndromes ultimately characterized by histologically similar tumors arising in patients and families with mutations in one of four genes: MEN1, RET, CDKN1B, and MAX." (PMID 39336996, 2024). "This case demonstrates the complexity of cancer evolution in RET-targeted therapy and the possibility of addressing such complexity using customized combination therapies that prolong tumor control." (PMID 38438731, 2024).
tumor (continued). "The inhibition of tumor growth by NSC311152 in vivo was mediated by the reduced protein expression of RET, c-Myc, Bcl-2 and cyclin D1 in tumor tissues evaluated using western blotting." (PMID 38791433, 2024). "In this first-in-human phase 1 study, SY-5007, a highly selective and potent RET inhibitor, demonstrated a manageable safety profile and promising anti-tumor efficacy in 122 patients with advanced solid tumors harboring activating RET alterations." (PMID 39489747, 2024). "CCDC6-RET, KIF5B- RET, RET V804M, and RET M918T are all gene fusions and mutations that are responsive to the anti-tumor activity of selpercatinib." (PMID 39518080, 2024). "A possible reason for this is that RET positive NSCLC is considered a “cold” tumor, similar to other types of oncogene-addicted NSCLCs, characterized by low PD-L1 expression and tumor mutational burden (TMB)." (PMID 38317126, 2024). "A retrospective analysis of the primary tumor material from 2016 and a tumor-infiltrated lymph node from the same period revealed the presence of RET gene rearrangement." (PMID 38539256, 2024). "These updated data continue to highlight the anti-tumor activity of selpercatinib against RET-positive tumors." (PMID 39518080, 2024). "The patients, who obtain RET alteration, have different tumor-infiltrating lymphocyte subpopulations." (PMID 38734621, 2024). "In vivo studies further support these findings, revealing dose-dependent and potent anti-tumor activity in various RET-driven xenografts models in mice." (PMID 39489747, 2024). "We further show that these properties translate into improved tumor control in an intracranial model of RET-driven cancer." (PMID 37743366, 2023). "Fixed effects model analysis showed that the combined ORR was 0.67 (95%CI: 0.64–0.70, P < 0.05), suggesting that RET-TKIs have an excellent tumor response." (PMID 37603207, 2023). "Both DNA and RNA sequencing of the resected tumor suggested the presence of intact RET kinase domain in the resulting chimeric protein." (PMID 37478265, 2023). "Mutant B-Raf proto-oncogene (BRAF) and RAS, and RET fusions were found to be the disease-causing alterations in about 80% of tumours in PTC: oncogenic BRAF (~60% of cases), H-RAS and N-RAS (~10%) and RET fusions (~5%)." (PMID 37207147, 2023). "Selpercatinib has been shown to inhibit KIF5B-RET 60 to 1300 times more than MKIs in engineered cells, and significant tumor regression has been seen in RET fusion-positive tumor mouse models." (PMID 37603207, 2023). "In a pan-cancer cohort, RET amplifications (defined as ≥6 copies of wild-type RET) were detected in 0.16% (145/91,466) of tumor samples, including 0.13% (15/11,622) of NSCLC cases." (PMID 37627175, 2023). "In this review, we discuss the biology of RET alterations and strategies to target these oncogenic drivers, including contemporaneous tumor agnostic approaches based on registrational data from the selpercatinib and pralsetinib trials." (PMID 37627175, 2023). "While RET short variant mutations are pathognomonic of 98% hereditary and 50% of sporadic medullary thyroid cancers (MTC), they are rarely reported in other tumor types." (PMID 36690680, 2023). "The RET gene is involved in kidney and nervous system development and even the formation of tumours." (PMID 37760531, 2023). "A phase I study of HS-10365 has assessed the safety, tolerability, PK and anti-tumor activity in RET-altered solid tumors (NCT05207787, accessed 3 November 2023), including RET fusion–positive NSCLC and RET-mutated MTC." (PMID 38201460, 2023). "In NSCLC, RET copy number gains (8.1%) and amplifications (2.8%; when defined as innumerable RET clusters, or ≥7 copies in >10% of tumor cells) are detected in a higher proportion of tumor samples when compared to RET rearrangements (0.7%)." (PMID 37627175, 2023). "The potential pivotal role of ERK1/2 in mediating adaptive resistance to TKI in RET fusion-positive tumor cells was supported by Ramen’s findings." (PMID 36768754, 2023).
tumor (continued). "In the mice treated with 50 mg/kg, the tumor volumes, weight and RET production all exhibited a dramatic decrease." (PMID 36646686, 2023). "The determination of a testing approach for RET abnormality is based on factors such as the type of changes to be screened (fusion vs. mutation), the quality and quantity of available tissue, the number of changes that may be screened based on tumor type, and cost considerations." (PMID 38001751, 2023). "The efficacy of selpercatinib was clinically significant in the tumor-agnostic population with RET fusion-positive, and its safety profile remained consistent with that observed in other indications." (PMID 38001751, 2023). "Second, we developed a LNM prediction nomogram based on the age, gender, tumor diameter, and RET alteration." (PMID 37081757, 2023). "Most recently, in September 2022, selpercatinib was granted regular approval for adult patients with locally advanced or metastatic NSCLC with a RET fusion and was granted accelerated approval for RET fusion–positive cancers in a tumor agnostic setting." (PMID 38201460, 2023). "miR-375 expression is a negative prognostic marker for MTC and miR-153-3p is a RET-regulated tumor suppressor in MTC." (PMID 37204852, 2023). "In 1 meta-analysis, the presence of a RET alteration in sporadic MTC was associated with an elevated risk for lymph node metastasis, advanced tumor stage and tumor recurrence." (PMID 37204852, 2023). "In a study using engineered cell lines and PDX models harboring KIF5B-RET, RET M918T, or RET V804M alterations, selpercatinib induced significant tumor regressions across models." (PMID 37627175, 2023). "The response to pralsetinib in RET fusion-positive NSCLC patients was also assessed based on the alterations/clearance of the level of the RET circulating tumor DNA (ctDNA) in blood samples." (PMID 37568193, 2023). "Multi-center, phase I/II clinical trials conducted by Drilon and Gainor have shown that Both Selpercatinib and Pralsetinib showed good tumor response in patients with RET rearrangement positive NSCLC and significantly extended disease-free survival." (PMID 37603207, 2023). "We provide a novel nomogram to predict the LNM for TC patients, including the features of patient's age, gender, tumor diameter, and RET alteration." (PMID 37081757, 2023). "Though with the coexistence of LCNEC and SCC, the tumor is basically adenocarcinoma with KIF5B/RET fusion." (PMID 37653509, 2023). "We found that the minimum amount of RNA needed for the detection of ALK, ROS1, RET fusion transcripts, and METΔex14 ranged between 1 and 10 pg·μL−1, corresponding to 0.1–0.01% fraction of tumor RNA." (PMID 37243883, 2023). "We provide a novel nomogram to predict the LNM for TC patients, concerns the features of patient's age, gender, tumor diameter, and RET alteration." (PMID 37081757, 2023). "Mutations or fusions involving RET can incite downstream signaling pathways such as RAS/MAPK, PI3K/AKT, or JNK, thereby promoting cell survival and tumor growth." (PMID 37927605, 2023). "This NBNR group included neoplasias encompassing genetic fusion events involving tyrosine kinases (RET, NTRK, ALK, ROS, etc.)." (PMID 37510219, 2023). "Subcutaneous implantation of a patient-derived BCBM xenograft into nude mice showed that either Afatinib or Cabozantinib was sufficient to neutralize tumor growth, further supporting RET inhibition as a possible strategy for BCBM therapy." (PMID 36918928, 2023). "In colorectal cancer, patients with RET-hypermethylated tumours showed significantly worse overall survival." (PMID 37835559, 2023). "Because of the insufficient activity of vandetanib in patients with no identified RET mutations, recently EMA restricted the vandetanib indication to patients with a RET-positive tumor." (PMID 37979019, 2023). "RET/PTC1 is found in 60–70% of cases and associated with more indolent tumours when comparing with RET/PTC3 that has been associated with radiation-induced tumours." (PMID 37374164, 2023).